SCIMP (SLP adaptor and CSK interacting membrane protein)
Description:
Lipid tetraspanin-associated transmembrane adapter/mediator that acts as a scaffold for Src-family kinases and other signaling proteins in immune cells. It is involved in major histocompatibility complex class II (MHC-II) signaling transduction in B cells, where it is required in generating the calcium response and enhancing ERK activity upon MHC-II stimulation. In dendritic cells, it is involved in sustaining CLEC7A/DECTIN1 signaling after CLEC7A activation by fungal beta-glucans (By similarity). It also acts as an agonist-inducible signaling adapter for TLR1, TLR2, TLR3, TLR4, and TLR7 by selectively enabling the expression of pro-inflammatory cytokines IL6 and IL12B in macrophages and acting as a scaffold for phosphorylation of Toll-like receptors by Src-family kinases (By similarity).
Synonyms: C17orf87; DTFT5783; UNQ5783; FLJ32580; MGC163426; MGC163428
Tractability: Antibody: UniProt places it where antibodies can reach, with high confidence; UniProt predicts a signal peptide or a membrane-spanning region; its Gene Ontology location is reachable by antibodies, with medium confidence.
Gene: Protein-coding gene on chromosome 17 (5,208,920 to 5,234,860, reverse strand). Ensembl gene ENSG00000161929.
Subcellular location: Cell membrane; Cytoplasmic vesicle, phagosome; Cell projection, ruffle; Cell projection, filopodium
Gene Ontology:
Molecular function: protein binding; molecular adaptor activity
Biological process: positive regulation of ERK1 and ERK2 cascade; cellular response to molecule of fungal origin; positive regulation of cytokine production involved in immune response; positive regulation of dendritic cell cytokine production; positive regulation of interleukin-12 production; positive regulation of interleukin-6 production; positive regulation of lipopolysaccharide-mediated signaling pathway; positive regulation of stress-activated MAPK cascade; toll-like receptor 3 signaling pathway; toll-like receptor 4 signaling pathway; toll-like receptor 7 signaling pathway; toll-like receptor TLR1:TLR2 signaling pathway
Cellular component: immunological synapse; leading edge membrane; membrane; plasma membrane; tetraspanin-enriched microdomain; uropod membrane; filopodium; phagocytic vesicle; receptor complex; ruffle
Genetic constraint (gnomAD): Loss-of-function variants: 13 observed, 16.32 expected, observed/expected ratio (o/e) 0.8, 90% interval 0.52 to 1.27. The upper end of that interval is the gene's LOEUF score, 1.27, which puts it in group 5 of 6, group 1 being the genes least tolerant of losing a copy. Missense variants: 119 observed, 146.86 expected, observed/expected ratio (o/e) 0.81, 90% interval 0.7 to 0.94. Synonymous variants: 44 observed, 51.65 expected, observed/expected ratio (o/e) 0.85, 90% interval 0.67 to 1.1.
Homologues: Orthologues: chimpanzee SCIMP (98% identical), macaque SCIMP (86% identical), dog SCIMP (74% identical), rabbit SCIMP (66% identical), mouse Scimp (61% identical), pig SCIMP (61% identical), rat Scimp (60% identical), guinea pig SCIMP (54% identical). Paralogues in human: MEI1 (21% identical), BCL2L11 (10% identical).
Diseases named in the same sentence as SCIMP in open-access papers:
SCIMP is named in the same sentence as 6 diseases in open-access papers, as found by Europe PMC text mining. Sharing a sentence is not in itself a finding about the gene and the disease. The quoted sentences say what the papers report.
pneumonia (2 papers, 2024). An acute, acute and chronic, or chronic inflammation focally or diffusely affecting the lung parenchyma, caused by an infection in one or both of the lungs (by bacteria, viruses, fungi, or mycoplasma.). "Moreover, a murine pneumonia model was established by bronchial perfusion of E. coli (2 × 106 colony-forming unit or CFU per mouse), and upregulated endogenous SCIMP protein expression was observed in the pulmonary tissue by immunohistochemistry (IHC)." (PMID 38263143, 2024).
Alzheimer disease (1 paper, 2025). A progressive, neurodegenerative disease characterized by loss of function and death of nerve cells in several areas of the brain leading to loss of cognitive function such as memory and language. "We dissect distributional regulatory effects at established Alzheimer’s Disease (AD) risk genes including PITRM1, TMEM106B, and the CHRNE/SCIMP/RABEP1 cluster, revealing complex context-dependent regulatory architecture missed by linear analysis." (PMID 41377971, 2025). "At Alzheimer’s disease (AD) risk loci, qQTL analysis revealed complex regulatory architecture including variance effects at PITRM1, lower-quantile-specific effects at TMEM106B partially explained by APOE ε4 interactions, and coordinated epigenetic regulation at loci harboring CHRNE/SCIMP/RABEP1." (PMID 41377971, 2025).
SCIMP also shares sentences with these, for which no sentence is quoted: autoimmune disease (1 paper); COVID-19 (1); infection (1); tumor (1).